HSPA5 (heat shock protein family A (Hsp70) member 5)
Diseases named in the same sentence as HSPA5 in open-access papers (continued):
Sharing a sentence is not in itself a finding about the gene and the disease.
hematoma (2 papers, 2019 to 2026). A hematoma is a collection of blood from a vascular structure into an extravascular space. "Both the hematoma-surrounding region and contralateral hemisphere showed substantially diminished signals for Hspa5, Hk2, and Tnf compared to earlier timepoints, with expression levels dropping to or below naive baseline values." (PMID 41601478, 2026).
keratoconus (2 papers, 2022 to 2024). A degenerative, structural disorder of the eye, characterized by a cone-shaped protrusion of the cornea. "Our research findings demonstrate a decrease in HSPA5 expression in keratoconus compared to control corneas, suggesting that ER stress may contribute to the susceptibility of keratoconus." (PMID 38830963, 2024). "The expression of CCR2, CDKN1A, HSPA5, MAPK8IP1, PPP1R15A, and VEGFA in individuals with keratoconus was significantly different from that in control subjects." (PMID 38830963, 2024). "Among the proteins identified in exosomes, frequently accepted markers of nanovesicles such as CD81 and various Hsp70 species were found, including HSPA2 in both types of exosomes, HSP1B in healthy ones, and HSPA5 and HSPA6 in keratoconus." (PMID 36289615, 2022).
laryngeal squamous cell carcinoma (2 papers, 2022 to 2025). A squamous cell carcinoma that arises from the larynx. "In laryngeal squamous cell carcinoma, HOTAIR sponges hsa-miR-30a-5p, thereby relieving the inhibition of its target GRP78 (HSPA5), which subsequently leads to increased PD-L1 protein levels." (PMID 41221298, 2025).
leiomyoma (2 papers, 2019 to 2025). A well-circumscribed benign smooth muscle neoplasm characterized by the presence of spindle cells with cigar-shaped nuclei, interlacing fascicles, and a whorled pattern. "The five patients shown in the figure are representative of the total seven patients included in the study, based on both 2-DE and Western blotting phosphorylation trend of HSPB1, HSPA5, and VINC (higher in leiomyoma compared to myometrium)." (PMID 31100862, 2019).
metastatic cancer (2 papers, 2015 to 2023). A carcinoma which has spread from the original site of growth to another anatomic site. "HSPA5 may also be important for tumor metastasis because it is elevated in metastatic cancer cell lines, lymph node metastasis, and knockdown of HSPA5 inhibits tumor cell invasion in vitro and growth and metastasis in xenograft models." (PMID 25609022, 2015).
primary Sjögren syndrome (2 papers, 2016 to 2022). "Our experiments confirmed the presence of HSPA5 in the conjunctival epithelium of Sjögren’s syndrome patients but, additionally, they showed the nuclear translocation of HSPA5." (PMID 35562919, 2022).
rectum adenocarcinoma (2 papers, 2020 to 2021). An adenocarcinoma arising from the rectum. "In addition, higher HSPA5 levels resulted in worsen survival probability in patients with rectum adenocarcinoma (p = 0.12 but showing the trend)." (PMID 33023006, 2020).
alopecia areata (1 paper, 2025). Loss of scalp and body hair involving microscopically inflammatory patchy areas. "Our results show that HSPA5 may play a role in hair follicle aging and hair loss, and it may provide new ideas for the treatment of alopecia areata by targeting the expression or function of HSPA5 to regulate apoptosis." (PMID 41380997, 2025). "The downregulation of HSPA5 indicated weakened inhibition of apoptosis, which was found to be related to alopecia areata." (PMID 41380997, 2025).
cerebellar degeneration (1 paper, 2014). Degeneration of the cerebellum. "Because complete elimination of HSPA5 in Purkinje cells leads to reduced cytosolic ubiquitination and accelerated cerebellar degeneration in a mouse model, HMGB1 could be a target of mutant TBP in SCA17, as well as NFYA." (PMID 25549101, 2014).
childhood asthma (1 paper, 2025). "The resistin protein-protein interaction network analysis further suggests that SQSTM1, HSPA5 and A2M might serve as the potential therapeutic targets in childhood asthma." (PMID 41550933, 2025). "SQSTM1, HSPA5, and A2M which directly interact with RETN could serve as the potential therapeutic targets in childhood asthma." (PMID 41550933, 2025).
chronic rheumatic heart disease (1 paper, 2021). "Fae and collaborators demonstrated PDIA3 and HSPA5 to be recognized by heart infiltrating and peripheral T cells in chronic rheumatic heart disease patients, suggesting that these proteins may be involved in an autoimmune-mediated tissue response as autoantigen targets of antibodies." (PMID 34885011, 2021).
fungal infection (1 paper, 2022). "HSPA5 is involved in protein folding in the endoplasmic reticulum, assists in fungal infection of epithelial cells, and has been implicated in both proliferation and apoptosis." (PMID 35756689, 2022).
gliosarcoma (1 paper, 2018). A rare histological variant of glioblastoma (WHO grade IV) characterized by a biphasic tissue pattern with alternating areas displaying glial and mesenchymal differentiation (WHO). "No previous data exist on the role of HSPA5 on pituitary function, but in a rat gliosarcoma cell line HSPA5 expression is induced by cAMP-responsive protein kinases." (PMID 29507682, 2018).
gout (1 paper, 2022). A condition characterized by painful swelling of the joints, which is caused by deposition of urate crystals. "Candidate targets of turmeric for gout were HSPA8, VCP, HSP90AB1, HSPA5, HSPA1B, NFKB1, and STUB1." (PMID 36276864, 2022).
hyperprolactinemia (1 paper, 2023). Abnormally high level of prolactin in the blood. "This increase may be explained by the observed hyperprolactinemia since prolactin and STAT5 are known transcriptional activators of CITED2, HSPA5 and PIM1." (PMID 36694114, 2023).
influenza (1 paper, 2025). An acute viral infection of the respiratory tract, occurring in isolated cases, in epidemics, or in pandemics; it is caused by serologically different strains of viruses (influenzaviruses) designated A, B, and C, has a 3-day incubation period, and usually lasts for 3 to 10 days. "Overall, the proteomic analysis suggests that HSPA5 may play a role in regulating chemotaxis, inflammatory responses, and cell death by necrosis and apoptosis during influenza infection, demanding further investigation." (PMID 41303479, 2025). "However, EGCG, a HSPA5 inhibitor significantly inhibits two different strains of Influenza in two different epithelial cell lines." (PMID 41303479, 2025). "Thus, a deeper understanding of HSPA5’s role in IAV biology will be essential for designing interventions that maximize antiviral efficacy while minimizing adverse effects, ultimately advancing preparedness against future influenza outbreaks and pandemics." (PMID 41303479, 2025).
kidney cancer (1 paper, 2021). Primary or metastatic malignant neoplasm involving the kidney. "The association of CALU with GPX4, HSPA5 and SLC7A11 in the pan-cancer data revealed a significant relationship between CALU and ferroptosis among various tumors, especially the breast, prostate and kidney cancers where ferroptosis was more commonly observed." (PMID 34150647, 2021).
knee osteoarthritis (1 paper, 2022). "It was found that HSPA5-rs12009 was significantly associated with knee osteoarthritis (KOA) severe progression in an exploratory cohort." (PMID 36686460, 2022).
legionellosis (1 paper, 2016). Any disease caused by Legionella bacteria. "Our major finding pathways- based network analysis between the patients and a normal one, include antigen processing and presentation (HSPA5, HSPA8), protein processing in the endoplasmic reticulum (HSP90B1, HSPA5, HSPA8) and legionellosis (HSPA8)." (PMID 27895852, 2016).
malnutrition (1 paper, 2020). Inadequate nutrition resulting from poor diet, malabsorption, or abnormal nutrient distribution. "The cluster formed CALR, HSPA5, P4HB and, PDIA6 is a potential indicator of maternal malnutrition on the endoplasmic reticulum dysfunction in the prostate of offspring since they act as the fundamental molecular machinery for correct protein folding and Ca2+ homeostasis." (PMID 33049715, 2020).
neuropathy (1 paper, 2018). A disorder affecting the nervous system that manifests with pain, tingling, numbness, and/or muscle weakness. "Functional GRP78 variants in heat shock protein family A (Hsp70) member 5 (HSPA5) genes are likely to have some influence on the gene expression, which results in the dysfunction of peripheral nerves and neuropathy." (PMID 29736170, 2018).
SARS-CoV infection (1 paper, 2021). "SARS-CoV infection has been shown to lead to ER stress and the up-regulation of HSPA5." (PMID 34966926, 2021).
thyroid (1 paper, 2025). "In the comparison between PTC and benign thyroid samples, SFN and CCNA1 were significantly upregulated, whereas FOS, HSPA5, JUN, CREB1, and MAP2K6 exhibited significant downregulation, supporting the findings obtained from the RT-qPCR analysis." (PMID 40722651, 2025).
tongue squamous cell carcinoma (1 paper, 2025). A squamous cell carcinoma that arises from the tongue. "Evodia lepta extract selectively induces ferroptosis in tongue squamous cell carcinoma cells through GPX4 and HSPA5 downregulation, while simultaneously reducing PD-L1 expression, suggesting both cytotoxic and immunotherapeutic potential." (PMID 41227330, 2025). "Evodia lepta extract selectively induces ferroptosis in tongue squamous cell carcinoma by downregulating GPX4 and HSPA5, while simultaneously reducing PD-L1 expression." (PMID 41227330, 2025).
Ventriculomegaly (1 paper, 2022). An increase in size of the ventricular system of the brain. "Specifically, HSPA5 displayed a log2 fold change (FC) of +0.65 in relation to echolucency and a log2 FC of +0.42 in relation to ventriculomegaly." (PMID 36389237, 2022).
cancer (669 papers, 2005 to 2026). A tumor composed of atypical neoplastic, often pleomorphic cells that invade other tissues. "Recent studies have shown that human ER luminal chaperone GRP78 (also known as Bip and encoded by the HSPA5 gene), an ortholog of Drosophila Hsc70-3, is up-regulated and translocated to the nucleus in cancer and stressed cells." (PMID 40261911, 2025). "In certain cancers, increased expression of HSPs, like HSPA5, is associated with a poor clinical prognosis and reduced response to treatment." (PMID 38494858, 2024). "Together with the strong expression of HSPA5 in NRF3‐deficient cancer cells of SCC patients, these results suggest HSPA5 inhibition as a treatment strategy for these malignancies in stratified cancer patients." (PMID 37807968, 2023). "Heat shock protein family A (HSP70) member 5 (HSPA5) is aberrantly expressed in various tumors and closely associated with the progression and prognosis of cancer." (PMID 36982218, 2023). "A pan-cancer analysis on the association of CALU with HSPA5, GPX4 and SLC7A11 further confirmed the potential involvement of CALU in the regulation of ferroptosis." (PMID 34150647, 2021). "Dysregulations of these stress proteins including HSPA5 are associated with many human diseases including cancers, immunological diseases, cardiovascular diseases, neurodegenerative diseases, obesity, stroke and infectious diseases 3-6." (PMID 33767597, 2021). "Since almost all cancer tissues had highly expressed HSPA5, this indicated that all tumor patients are susceptible to the SARS-CoV-2 infection, implying the clinical significance of the role of HSPA5 expression." (PMID 33767597, 2021). "HSPA5 overexpression in cancer is associated with poor prognosis and drug resistance, and represents a novel therapeutic target." (PMID 29507682, 2018). "When E1A was expressed in cancer cells, it associated with p300 to reduce acetylated HSPA5 levels and enhanced its binding to GP78, thereby promoting the HSPA5 ubiquitination and subsequent inhibition of metastasis." (PMID 25301734, 2014). "Three different siRNAs or siRNA pools each for HSPA1A/HSPA1B and HSPA8 and, in addition, siRNA pools against HSPA2, which is expressed in a tissue specific manner and was implicated in cancer cell survival, and HSPA5 were utilized." (PMID 24265689, 2013). "Furthermore, knockdown of HSPA5 via siRNA reduced the oncogenic KRAS protein level in various KRAS mutated cancers." (PMID 37189349, 2023). "Upon loss of NRF3, HSPA5 levels increased, thereby promoting cancer cell survival and migration." (PMID 37807968, 2023). "The second μ-17-specific cancer-associated module comprises endoplasmic reticulum (ER) molecular chaperones (PDIA4, PDIA6, GANAB) and heat shock proteins (HYOU1, HSPA5, DNAJB11)." (PMID 41373892, 2025). "In the progression of cancer, HSPA5 is translocated to the cell surface (csHSPA5) where it activates key signaling pathways, such as the PI3K/AKT and MAPK/ERK signaling pathways, which promote cell survival and inhibit apoptosis." (PMID 40765821, 2025). "This upregulation of cell-surface HSPA5 has cytoprotective effects for cancer cells, making the HSPA5 pathway a promising candidate to target." (PMID 41301006, 2025). "HSPA5 was known to participate in numerous cancers; however, the diverse levels of its expression exhibit substantial variations in the prognosis and advancement of distinct cancer types." (PMID 40255561, 2025). "The ER-resident chaperone HSPA5 is responsible for tumorigenesis in many organs via overexpression and translocating to the cell surface in many cancer cells." (PMID 41301006, 2025). "Overall, HSPA5 suppresses ferroptosis in cancer cells while facilitating tumor cell migration and metastasis." (PMID 40255561, 2025). "In many cancers, patients with HSPA5-overexpressing tumors have significantly worse prognosis than those with low-expressing tumors." (PMID 41301006, 2025).
cancer (continued). "The overexpression of HSPA5 has also been shown to induce varying patient prognoses across different cancers." (PMID 41301006, 2025). "HSPA5 is normally retained in the ER by its KDEL motif, but in the progression of cancer, excess HSPA5 in the ER is translocated to the cell surface (csHSPA5) that stimulates the PI3K/AKT pathways, promoting promote cell survival and inhibit apoptosis." (PMID 40765821, 2025). "Our data revealed that the overexpression of SBSPON can slightly increase the amount of HSPA5 protein, which seems to contradict the anti-cancer function of SBSPON." (PMID 40765821, 2025). "In colorectal cancer, HSPA5 suppresses ferroptosis in tumor cells to enhance cancer progression by preserving GPX4 stability." (PMID 40255561, 2025). "Overactivation of IFN-α/IFNAR2 binding promoted the worsening of Tex exhaustion and the resistance of HSPA5+ malignant tumor cells to IFN-α." (PMID 40990011, 2025). "HSPA5, a glucose-regulated protein first identified in 1974, is widely recognized for its overexpression in a variety of cancers and has emerged as a prognostic biomarker of disease and predictor of infiltrating immune cells in the tumor microenvironment." (PMID 39858470, 2025). "Simultaneous and sequential cs-HSPA5 targeting, in conjunction with irradiation, therefore presents an enticing one-two punch strategy for managing malignant tumors." (PMID 41301006, 2025). "Several cancers inherently demonstrate a high expression of cell-surface HSPA5 (cs-HSPA5)—pancreatic, lung, gastric, and esophageal, among others." (PMID 41301006, 2025). "While the precise mechanisms are not fully understood, studies have shown that HSPA5 plays a role in modulating ferroptosis in different types of cancer cells." (PMID 38494858, 2024). "The mRNA levels of HSPA5 were upregulated in several cancer types, and the GEO database showed that the mRNA expression level of HSPA5 in NSCLC tissues was significantly higher than that in normal lung tissues (P < 0.001)." (PMID 38521810, 2024). "As a key molecule in the unfolded protein response (UPR) pathway, the transcriptional activation of HSPA5 is involved in mediating the malignant biological behavior of cancer cells." (PMID 38521810, 2024). "HSPA5 increased expression is considered an essential indicator of poor prognosis and reduced survival rate in cancer patients." (PMID 39323470, 2024). "It has been shown to contribute to tumorigenesis and anti-apoptotic properties, evidenced by significantly reduced survival and increased apoptosis of cancer cell lines with inhibition of HSPA5." (PMID 38732562, 2024). "The therapeutic and prognostic significances and prospects in cancers and COVID-19 disease by targeting HSPA5 are also discussed." (PMID 37275848, 2023). "The association between the abnormal expression of heat shock protein family A (HSP70) member 5 (HSPA5) and the progression and prognosis of cancer in multiple tumors has been a focus in cancer research." (PMID 37886960, 2023). "This work clearly defined a complex genome-wide HSPA5-RNA interaction map in a human cancer cell line and indicated that HSPA5 binds to the exon-intron boundary and regulates various alternative splicing (AS) events." (PMID 37156995, 2023). "In the current study, we review the newest research progresses on cell surface protein HSPA5 expressions, functions, and mechanisms for cancers and SARS-CoV-2 invasion." (PMID 37275848, 2023). "Altogether, we reviewed the high expression of HSPA5 in the most cancers and the possibility of being invaded by the virus as a new coronavirus receptor." (PMID 37275848, 2023). "HSPA5 and RCN1 are substantially elevated in cancer, and their levels associate with progression of malignancy." (PMID 37651191, 2023). "Next, we also explored HSPA2 and HSPA5 expression based on nodal metastasis status and individual cancer stage." (PMID 36982218, 2023).